ACLY (ATP citrate lyase)
Diseases named in the same sentence as ACLY in open-access papers (continued):
Sharing a sentence is not in itself a finding about the gene and the disease.
cancer (continued). "PERK regulates fatty acid synthase (FAS, a key de novo lipogenesis enzyme required to make fatty acids for cancer cell membranes), ATP-citrate lyase (ACL, another important enzyme that creates acetyl-CoA for fatty acid and cholesterol synthesis), SCD1, and SREB1." (PMID 41301006, 2025). "ACLY expression is upregulated in both breast and prostate cancers." (PMID 40214422, 2025). "This highlights the potential therapeutic value of targeting USP13 and ACLY in cancer treatment." (PMID 41330897, 2025). "Inhibition of SLC25A1 or ACLY leads to impaired cancer cell proliferation, differentiation, and sensitization to immune therapy, highlighting their role as potential effective targets for anti-cancer strategy." (PMID 39881208, 2025). "Moreover, the inhibition of ACLY has also been found to induce apoptotic cell death in other cancers." (PMID 40214422, 2025). "Similarly, enzymes involved in glutamine metabolism (e.g., GLS1, GDH) and lipid biosynthesis (e.g., FASN, ACLY) further underscore the metabolic dependencies that distinguish cancer cells from normal counterparts." (PMID 41154605, 2025). "Reduced ACLY activity has modest acute cytotoxic effects if applied directly to cardiomyocytes, these cells being more sensitive to ACLY inhibition than what is reported from proliferative cells such as cancer, vascular smooth muscle cells, stem cells, or myofibroblasts." (PMID 40499285, 2025). "Due to its crucial involvement in lipid production, ACLY inhibitors, initially designed for metabolic conditions like hypercholesterolemia and type 2 diabetes, are now being explored as potential treatments for cancer." (PMID 38933330, 2024). "In addition, our analyses revealed that ACLY expression levels are negatively correlated with cancer stemness, immune infiltration, and the efficacy of immunotherapy in CCA." (PMID 39399493, 2024). "With limited evidence that ACLY splicing impacts its canonical functions, we returned to TCGA to generate a new hypothesis to explain the association between ACLY PSI, cancer, and patient survival." (PMID 38815867, 2024). "Therefore, there has been considerable interest in targeting ACLY with anti-cancer drugs since many cancer cells rely on its activity in fatty acid metabolism, cholesterol biosynthesis, and protein acetylation and prenylation." (PMID 38216787, 2024). "However, in recent years, ACLY inhibitors have attracted attention as promising anti-cancer drugs as more and more evidence suggests that cancer is a metabolic disease as well as a genetic one." (PMID 38755125, 2024). "Additionally, our analyses revealed that ACLY expression levels are negatively correlated with cancer stemness, immune infiltration, and the efficacy of immunotherapy in CCA." (PMID 39399493, 2024). "We first investigated the expression of ACLY in pan‐cancer through the TCGA database Sangerbox." (PMID 38426936, 2024). "We examined the expression of ACLY in normal and tumor tissues across a range of cancers." (PMID 39399493, 2024). "We found that ACLY was found to be highly expressed in a variety of cancers." (PMID 38426936, 2024). "In contrast, the expression of ACLY was negatively correlated with hematopoietic stem cells, myeloid dendritic cells, endothelial cells, naïve CD8+ T cells, central memory CD8+ T cells, M1 macrophages, and cancer-associated fibroblasts." (PMID 39399493, 2024). "As a crucial convertor of CoA, ACLY ubiquitination may modulate metabolic–epigenetic remodeling inside cancer cells." (PMID 37190313, 2023). "ACLY overexpression in a variety of cancers indirectly destroys citrate binding by altering the citrate binding site of the enzyme, which is one of the options for cancer treatment." (PMID 38189049, 2023). "However, looking to the future, ACLY is also of interest as a potential target in oncology, and given the metabolic plasticity of cancer cells and the ability to shift between nutrient sources, potential roles of CrAT and CrOT should be considered." (PMID 37134161, 2023).
cancer (continued). "Further research is needed to determine whether ACLY inhibition similarly inhibits cell death induced by other anti-cancer agents." (PMID 37899460, 2023). "The combination of an AMPK activator and an ACLY inhibitor may be another strategy for cancer treatment." (PMID 37056351, 2023). "Our findings demonstrate that the pharmacological co-inhibition of PLK1 and ACLY significantly suppresses pan-cancer cell proliferation compared to single-agent treatment and that this combination downregulated UBE2C mRNA and protein expression, which revealed a novel potential molecular mechanism." (PMID 37958642, 2023). "The mechanism underlying these effects may be that miR-22 reduced the ability of de novo lipid synthesis by inhibiting the expression of ACLY, thus inhibiting the proliferation and invasion of cancer cells." (PMID 37056351, 2023). "Furthermore, the global levels of histone acetylation in cancer cells are also dependent on nuclear acetyl-CoA production by ACLY." (PMID 36299478, 2022). "Interestingly, ACLY inhibitors have been used to treat metabolic disorders, and scientists are now trying to apply these inhibitors to cancer treatment." (PMID 39086974, 2022). "Moreover, recent studies have indicated the crucial role of acetyl-CoA in cancer metabolic pathways, suggesting that targeting acetyl-CoA metabolic pathway mediated by ACLY is likely to become a new and efficient anticancer strategy." (PMID 39086974, 2022). "Interestingly, some enzymes associated with fatty acid synthesis, including ATP citrate lyase, Acetyl-CoA carboxylase (ACC) and fatty acid synthase (FASN), are upregulated in some cancers." (PMID 36230935, 2022). "ACLY inhibition brings to changes in cancer cell metabolism." (PMID 36578540, 2022). "SREBPs transcriptionally activates enzymes involved in lipogenesis processes in cancer cells, including ATP citrate lyase (ACLY), acetyl-CoA carboxylase (ACC), fatty acid synthase (FASN), and acyl-CoA synthetase (ACS) which play significant roles in the process of lipid biosynthesis." (PMID 35646898, 2022). "Considering that AKT/mTOR pathway has been well established to play a central role in the regulation of cell lipid metabolism, we hypothesized that ACLY overexpression may activate AKT/mTOR pathway to promote cancer development." (PMID 36064336, 2022). "Several studies have recently focused on ACLY as a central metabolic enzyme in cancer." (PMID 36077475, 2022). "ACLY significantly promoted GC lipid metabolism and increased cancer cell proliferation." (PMID 36064336, 2022). "Inhibition of ACLY in KRas-driven cancer cells in the absence of serum resulted in loss of cell viability." (PMID 36269753, 2022). "ACLY links sugar- or glycol-metabolism to lipid metabolism, illustrating the important relationship between elevated glucose uptake and lipid metabolism in cancer cells." (PMID 35634242, 2022). "ACLY is also responsible for increased cancer stemness, cancer cell adhesion and migration." (PMID 35646898, 2022). "Inactivation of SIRT6 in cancer cells results in the accumulation of nuclear ACLY protein, increasing nuclear acetyl-CoA, which in turn drives site-specific histone acetylation and the expression of cancer cell adhesion and migration genes that promote tumor aggressiveness." (PMID 36171897, 2022). "We therefore investigated whether Gln deprivation impacted the effect of the ACLY inhibitor SB-204990 on KRas-driven cancer cells in the presence of serum." (PMID 36269753, 2022). "ACLY is upregulated in cancer cells and is required for their growth." (PMID 35178152, 2022). "ACLY is a cytoplasmic homologous tetramer composed of four polypeptide chains and acts as a metabolic enzyme involved in fatty acid synthesis in rapidly proliferating cancer cells." (PMID 35203617, 2022). "This suggests that inhibition of GOT along with ACLY inhibition could be a viable therapeutic option for treating KRas-driven cancers where there is a dependence on GOT to generate α-KG." (PMID 36269753, 2022).
cancer (continued). "Although no formal studies show that ACLY can induce YAP/TAZ activation, we would like to propose that ACLY may promote YAP/TAZ by two indirect mechanisms (but further studies are required to show whether they really occur in cancer cells)." (PMID 35626081, 2022). "Moreover, upregulation of ACLY and the Wnt/β-catenin pathway indicates that at the advanced stage of cancer, cells in the organoids undergo EMT, an essential element of invasiveness and metastasis." (PMID 36139896, 2022). "In addition, ACLY inhibition has emerged as a new therapeutic strategy for cancer, where ACLY inhibition blocks lipid synthesis and cellular proliferation." (PMID 36504724, 2022). "In addition, ACLY can promote the EMT phenotype in cancer cells (presumably by regulating Snail expression) and stemness." (PMID 34205414, 2021). "Besides regulating cancer metabolism, the importance of ACLY in mediating histone acetylation and gene expression profiles in cancer cells has also been recognized." (PMID 34573442, 2021). "The inactivation of SIRT6 in cancer cells leads to the accumulation of nuclear ACLY protein and increases nuclear acetyl-CoA pools, which in turn drive locus-specific histone acetylation and the expression of cancer cell adhesion and migration genes that promote tumor invasiveness." (PMID 34573442, 2021). "Moreover, ACLY is known to be highly expressed in many types of cancer cells, supporting proliferation through de novo lipogenesis, and making this enzyme a promising target of anti-cancer drugs." (PMID 33679780, 2021). "It was further demonstrated that 3,5-bisbromoemodin notably reduced cancer stemness in the 3D spheroid assay, and showed a comparable anti-proliferative activity against A549 cell to shRNA-mediated ATP citrate lyase knockdown, therefore making it an encouraging prodrug for tumor therapy." (PMID 34629100, 2021). "Notably, glucose-dependent cancer cell lines were more sensitive to ACLY knockdown or inhibition because part of the increased proliferation arises from glucose-dependent acetyl-CoA production by ACLY." (PMID 33679780, 2021). "Tumor tissues may have aberrant activation of de novo lipogenesis due to an overexpression of fatty acid synthase (FASN), ATP citrate lyase (ACLY), and acetyl-CoA carboxylase (ACC), which is associated with unfavorable cancer outcomes." (PMID 34476174, 2021). "Interestingly, the low citrate levels observed in malignant mesothelioma cells can be restored by microRNA-126 overexpression, a treatment which efficiently suppresses tumor growth, and inactivates ACLY and the insulin receptor substrate-1 (IRS-1)/Akt pathway." (PMID 34205414, 2021). "In several types of tumors, transcriptomic regulation of ACLY proves to be aberrantly activated, and its pharmacological or genetic inhibition significantly inhibited the proliferation and induced apoptosis of cancer cells." (PMID 34344378, 2021). "Inhibition of ACLY in SIRT6-deficient cells reversed the dysregulated expression and histone hyperacetylation and prevented the migration and adhesion phenotypes of SIRT6-deficient cancer cells." (PMID 34573442, 2021). "This aligns with our finding that the silencing of PEG3 might upregulate the expression levels of ACLY, which might be required for the high demand of lipids for the rapidly dividing cancer cells." (PMID 34048454, 2021). "The inhibition of the ACLY produces cytotoxic effects via disrupting FA synthesis, and thus the inhibitors of ACLY enzyme may hold therapeutic hopes for patients with malignancies." (PMID 36046117, 2021). "ACLY is also indicated as a fundamental factor of cancer stemness." (PMID 32641978, 2020). "There are also evidences that present ACLY as a promising target for cancer treatment." (PMID 32597160, 2020).
cancer (continued). "A similar phenotype was observed in cancer cells that share a sensitivity to the ACLY inhibitor HC, and we propose that citrate drives basal MICA expression by providing acetyl-CoA for histone acetylation that can modify chromatin structure around the MICA transcription start site." (PMID 32849657, 2020). "In human cancer cells, expression of ACLY and ACC is also markedly increased." (PMID 32947972, 2020). "ACLY presents elevated levels of activity and expression in several types of cancers." (PMID 33364199, 2020). "ATP-citrate lyase (ACLY), which regulates the availability of acetyl-CoA by catalyzing the conversion of oxidation-derived mitochondrial citrate into acetyl-CoA and oxaloacetate, is upregulated in several cancers." (PMID 32722390, 2020). "Cancer cells develop capable de novo FAS machinery with an increase in the activity of key lipogenic enzymes such as adenosine triphosphate (ATP)-citrate lyase (ACLY), acetyl-CoA carboxylase (ACC), CoA carboxylase (ACACA), fatty acid synthase (FASN), and SCD." (PMID 33364199, 2020). "De novo synthesis of FA is activated in cancer cell, which is catalyzed by ATP citrate lyase (ACLY), acetyl-CoA carboxylase (ACC) and fatty acid synthase (FASN), then converted to monounsaturated FA (MUFA) to generate triacylglycerol (TAG), the composition of LDs, by stearoyl-CoA desaturase (SCD)." (PMID 31777589, 2019). "Furthermore, increased expression and elevated activity of ACLY has been reported in several cancers including non-small cell lung carcinoma." (PMID 31534141, 2019). "In cancer cells, inhibition of ACLY might affect both fatty acid elongation in the endoplasmic reticulum and fatty acid oxidation in the mitochondria." (PMID 29361784, 2018). "ACLY is known to be partially present in the nuclear fraction of different cancer cell lines." (PMID 30568658, 2018). "Studies with C-14 glucose have shown that in cancer cells most fatty acids come froma high rate of de novo synthesis, necessary for a very active membrane biogenesis, and inhibition of ATP-citrate lyase produced inhibition of tumorproliferation in vitro and reduced in vivo xenograft tumor growth." (PMID 29258346, 2018). "ACLY inhibition also reduces proliferation of several cancer cells." (PMID 29295482, 2017). "ACLY was upregulated whereas ACO2 was downregulated in the MDR cancer cell models." (PMID 28303926, 2017). "However, ACLY is often upregulated or activated in human cancers, including lung, prostate, bladder, breast, liver, stomach and colon tumours." (PMID 27892457, 2016). "Moreover, miR-22 was proved to attenuate cancer cell proliferation and invasion, as well as promote cell apoptosis via inhibiting ACLY." (PMID 27317765, 2016). "Specifically, we showed that blocking de novo lipogenesis through the genetic depletion of ACLY or ACC1 protected multiple cancer cells from hypoxia-induced apoptosis through increased levels of α-ketoglutarate and the inhibition of ETV4 and its transcriptional activities." (PMID 26452058, 2015). "Different localization of ACLY may therefore reflect different activities within the cell, i.e. cytoplasmic ACLY is predominantly involved in cancer cell metabolism, while nuclear ACLY is predominantly involved in regulation of gene expression." (PMID 25962060, 2015). "Distinctive elevation of ACLY expression and activity has been reported in several types of cancer." (PMID 25890184, 2015). "ACLY converts cytosolic citrate to acetyl CoA, which promotes cancer cell proliferation." (PMID 25277207, 2014).
cancer (continued). "Of note, this type of compensation that occurs during the therapeutic targeting of lipogenesis-related enzymes such as ACLY might be unacceptable for cancer treatment." (PMID 25246709, 2014). "Furthermore, the overexpression of genes involved in fatty acid synthesis, such as the fatty acid synthase (FASN), acetyl-CoA carboxylase alpha (ACACA) and, the ATP citrate lyase (ACLY) can induce the development and progression of cancer." (PMID 24958265, 2013). "Furthermore, lipogenic enzymes that function upstream of FASN such as acetyl-CoA carboxylase-a (ACACA) and ATP citrate lyase (ACL) are also elevated in various cancers." (PMID 22266777, 2012). "Thus, taking into account this information in the computational model, the inhibition of ATP citrate lyase in the cytoplasm prevents cancer cell proliferation and tumor growth due to its role in lipid biosynthesis." (PMID 23316163, 2012). "Consistent with published findings, inhibition of ATP citrate lyase participating in conversion of mitochondria-derived citrate into acetyl-coenzyme A in cytoplasm prevents cancer cell proliferation and tumor growth due to its central role as a precursor for lipids." (PMID 20811631, 2010). "Therefore, since ACLY inhibition may carry an immunosuppressive effect, ACLY inhibitor monotherapy for cancers in preclinical models and clinical trials needs careful consideration and evaluation." (PMID 41306968, 2025). "Pharmacological targeting of SLC25A1 and ACLY sensitizes cancer cells to ferroptosis and inhibits tumor growth both in vitro and in vivo, suggesting that an in-depth study of this pathway may provide a new strategy for ferroptosis-targeted cancer treatment." (PMID 39881208, 2025). "The effect of AKT on histone acetylation is mediated by the metabolic enzyme ATP-citrate lyase, and the level of pAKT is significantly correlated with histone acetylation markers, indicating that acetyl-CoA metabolism is a key determinant of histone acetylation levels in cancer cells." (PMID 39588377, 2024). "Blocking ACLY activity reduces the growth of cancer cells both in laboratory settings and living organisms, suggesting that this enzyme could be a promising target for cancer treatment." (PMID 38933330, 2024). "Thus, ACLY appears as a potential target for cancer therapy." (PMID 37122003, 2023). "This article constructed a genetic score comprising independent genetic variations in genes encoding ATP citrate lyase (ACLY) and HMGCR, and explored the causal association between these scores and plasma lipid levels, lipoprotein levels, as well as cardiovascular events and cancer risk." (PMID 37724687, 2023). "Moreover, using a phosphoproteomics approach, we previously assessed the enzymatic activity of three enzymes associated with cancer and only present in sEVs derived from the cancerous cell lines MCF7 and MDA-MB-231: ATP citrate lyase (ACLY), sirtuin-1 (SIRT1) and sirtuin-6 (SIRT6)." (PMID 37189694, 2023). "Thus, ACLY is regarded as a central metabolic enzyme in cancer and may be a putative target for overcoming drug resistance." (PMID 36359776, 2022). "Besides, blocking ACLY sensitized cancer cells to chemotherapy by suppressing stem cell features." (PMID 35646898, 2022). "Whereas no studies directly addressed the impact of ACLY on de novo lipogenesis in macrophages, ACLY knockout THP-1 monocytic cells exhibited delayed cell growth, likely due to deficiencies in de novo lipogenesis, as previously observed in other cancer cell lines." (PMID 33679780, 2021). "However, given the broad bioenergetic roles of ACLY, and its known upregulation in cancer cells, the H2S-ACLY axis may have further bioenergetic and metabolic implications." (PMID 33499368, 2021).